CD4 (CD4 molecule)
Diseases named in the same sentence as CD4 in open-access papers (continued):
Sharing a sentence is not in itself a finding about the gene and the disease.
AIDS (continued). "In the absence of therapy, infected patients undergo progressive destruction of CD4+ T lymphocytes, leading to AIDS and death due to opportunistic infections." (PMID 29061947, 2015). "In this model, the death rate is dependent on time since infection; the parameter dj is the additional AIDS-related death rate of patients who have crossed the low CD4 count threshold." (PMID 26609066, 2015). "The overall AIDS progression rate underwent a steady reduction after 2010 (from 38.1 to 25.9 %) as the treatment was available to patients with a CD4+ T-cell count of 350 cells/mm3." (PMID 26413133, 2015). "In conclusion, HIV progression to AIDS was affected by the patient’s age at diagnosis, transmission routes and baseline CD4+ T-cell counts." (PMID 26413133, 2015). "Higher proportions of ocular manifestations were detected in HIV/AIDS patients with low CD4 counts and low duration on ART and in advanced stage of the diseases." (PMID 26000175, 2015). "Highly active antiretroviral therapy (HAART) significantly improves the prognosis of HIV-infected persons by reducing HIV viral load, increasing CD4+ lymphocyte counts and delaying progression to AIDS, ultimately reducing mortality rates." (PMID 25886530, 2015). "It should be noted, however, that this is a population-based descriptive investigation, including 40.9 % of PWA with less than 50 CD4 cell count at AIDS diagnosis in contrast, for instance, with a median of 280 CD4 cell count at enrolment in the cited trial." (PMID 26067992, 2015). "The first stage limits HIV infection to within one year, with two intermediate stages that include chronically infected individuals, and a fourth stage which corresponds to AIDS (as defined by a CD4+ < 200 copies/mL)." (PMID 26512688, 2015). "AIDS or death event rates were 0.52 and 0.79 per 1,000 person years for these two CD4+ strata; death rates were 0.24 and 0.38 per 1,000 person years, respectively." (PMID 25856495, 2015). "The CD4 count is a strong predictor of HIV progression to AIDS and death, and is considered the best laboratory marker for deciding when to initiate ART." (PMID 25790185, 2015). "After adjusting for other covariates, patients were more likely to receive ART if they were older, female, had a lower initial CD4 cell count, had tuberculosis or were AIDS stage at baseline." (PMID 26213959, 2015). "For AIDS-related deaths (n = 798), statistically significant factors included CD4 count <200 cells/mm3 at the time of cART initiation (AOR 1.94, 95%CI 1.24–3.05), ART naïve (AOR 1.69, 95%CI 1.09–2.61; p = 0.019) and age <39 years (AOR 2.96, 95%CI 1.77–4.96)." (PMID 26506621, 2015). "Diagnosed with HIV from 2011 to 2012 and having a higher CD4+ cell count (350–500 cells/mm3; or >500 cells/mm3) at baseline were independently associated with lower rates of HIV progression to AIDS [HR = 0.382, 0.380, 0.187, P < 0.001]." (PMID 26413133, 2015). "The subjects selected for inclusion in this study all chose not to receive antiretroviral treatment in acute or early infection, and remained untreated until progression towards AIDS, evidenced by a substantial decline in their circulating CD4+ T cell count." (PMID 25837979, 2015). "Progression to an AIDS-defining event has been significantly and independently associated not only with HIV RNA viral load and CD4+ T cell count, but also with CMV DNA." (PMID 26441939, 2015). "The results from our study suggest that increasing the CD4+ T-cell count necessary to begin HAART treatment is an effective way to delay AIDS progression among PLHIV." (PMID 26413133, 2015). "The previous national guideline recommended to initiating ART in the patients with a history of an AIDS-defining illness or CD4 cell count <350 cells/mm3." (PMID 25908935, 2015).
AIDS (continued). "Other studies have shown that CD4+ proliferation correlates with viral load; it has been suggested that this is because proliferating (Ki67+) CD4+ T-cells can efficiently support virus replication and lead to more rapid progression to AIDS." (PMID 26083409, 2015). "Unlike the situation in SIV-infected monkeys, a previous study indicated that there were high levels of Enterobacteriales and Bacteroidales in HIV/AIDS patients, which correlated with the depletion of CD4+ T cells and the immune activation." (PMID 26540050, 2015). "The reduction of viral load results in slow decline of CD4+ T cell counts and delayed progression to AIDS." (PMID 26617607, 2015). "Surveys conducted since the onset of the HIV/AIDS pandemic have consistently shown that OPC is closely correlated to reduced CD4+ T-cell counts in peripheral blood." (PMID 26110288, 2015). "Deep vein thrombosis (DVT) is 10 times more prevalent in HIV and AIDS patients than in the general population and is more common in patients with severe immune suppression (CD4 < 200 cells/mL)." (PMID 26245588, 2015). "Several factors, including mode of transmission, region, age and CD4+ T-cell count at baseline were related to the rate of AIDS progression in HIV-positive patients." (PMID 26413133, 2015). "Hazardous or harmful alcohol use and problematic drug use predicted missing and stopping ARVs which, in turn, was associated with a decrease in CD4 counts and more rapid HIV-disease progression and poorer health outcomes in people living with HIV/AIDS (PLWHA)." (PMID 25933422, 2015). "A marker of PIA is a CD4/CD8 ratio below 1.0 and the magnitude of decrease in CD4/CD8 ratio is directly associated with risk of non-AIDS events or death." (PMID 26355305, 2015). "In Brazil, among AIDS patients with CD4+ cell counts <200 cells/mm3, 50.7% had oral candidiasis, particularly of the pseudomembranous form." (PMID 25745611, 2015). "The incidence of anemia was strongly and consistently associated with the progression of HIV disease as measured by diagnosis of an AIDS-defining opportunistic illness and measurement of a CD4 count of 200 cells/μl." (PMID 25857950, 2015). "A standard Bayesian model can be fitted to estimate the probability of an individual being in one of the four stages conditional on the frequency of ambiguous sites in the HIV-1 pol gene, the CD4+ cell count and a concurrent AIDS diagnosis." (PMID 26512688, 2015). "The main risk factors of early mortality were older age, use of injection drugs, a very low CD4 cell count and the presence of a number of life threatening conditions at AIDS diagnosis." (PMID 26067992, 2015). "The HIV-infected individual found to cluster with the AIDS patients in the manual data analysis had a relatively high CD4/CD8 ratio." (PMID 26402620, 2015). "PML was previously thought to occur exclusively in patients with HIV/AIDS (CD4 < 500/mcl), and approximately 85% of cases have coexisting HIV infection." (PMID 26788389, 2015). "It is explained by the low CD4 counts at baseline, the type of TB cases, incidence of new AIDS defining illnesses and other co morbidities, quality of medical care, socioeconomic as well as geographical differences." (PMID 25966339, 2015). "Older studies have demonstrated that AIDS development in untreated HIV infection is highly predicted by longitudinal assessment of the CD4/CD8 ratio, whereas the CD4/CD8 ratio in treated individuals is related to the risk of the comorbidities." (PMID 26402620, 2015). "Compared with the index of HIV viral loads, the CD4 + T cell count is currently the more popular measure of efficacy in TCM clinical trials for AIDS treatment." (PMID 26699285, 2015). "Some experience rapid CD4+ T-cell decline and develop AIDS within a few months or years, whereas others remain AIDS-free for over 35 years." (PMID 26609066, 2015). "Following HIV infection, women generally exhibit lower viral loads and higher CD4 counts than men, but paradoxically progress faster to AIDS." (PMID 26267144, 2015).
AIDS (continued). "Human immunodeficiency virus type 1 (HIV-1) is the etiological agent of acquired immunodeficiency syndrome (AIDS), which specifically infects CD4+ T-cells, macrophages and dendritic cells." (PMID 26362536, 2015). "Initiation of ART increased from 27%/49% to 91%/89% among all cases (all p < 0.001) and from 39%/62% to 94%/90% among individuals with CD4 count ≤ 350 cells/mm3 or AIDS (all p < 0.001)." (PMID 26348214, 2015). "In this study, history of eye problem, CD4 count, and visual acuity of the eye were factors associated with HIV/AIDS related ocular manifestation." (PMID 26000175, 2015). "Late initiation was defined as a CD4 count <200 cells/mm3 or an AIDS-defining illness before ART initiation (baseline)." (PMID 26443752, 2015). "HIV-infected women exhibit lower viral loads and higher CD4 counts than men, but progress faster to AIDS." (PMID 26267144, 2015). "Differences in antibody levels among HIV positives and negative individuals have been reported to occur in later stages of HIV/AIDS when the CD4+ cell levels drop to less than 200/uL." (PMID 25906165, 2015). "Some of the characteristics herein investigated have been previously recognized as risk factors for mortality of PWA, namely injecting drug use, older age, a low number of CD4 cells at AIDS diagnosis, and severe AIDS-defining diseases." (PMID 26067992, 2015). "In resource-limited countries, there are fewer cohort studies that compare rates of mortality and AIDS among participants in latest CD4+ strata above 350 cells." (PMID 25856495, 2015). "Overall, 4274 participants (48%) initiated ART with a CD4 count <200 cells/mm3 or AIDS-defining illness." (PMID 26443752, 2015). "In the Multicenter AIDS Cohort Study (MACS) the mean CD4 count of newly diagnosed HIV dementia cases rose from 151 in 1992 to 518 in 2001." (PMID 26347017, 2015). "Among these index cases four had a CD4 count lower than 200 cells/mm3 (one of these met criteria for AIDS), three were between 200–349, five were between 350 and 500 cell/mm3, and twelve more than 500 cells/mm3." (PMID 25849451, 2015). "Effect of HCV co-infection on time from HIV seroconversion to CD4<350 cells/mm3, AIDS or death by HCV infection status and HCV infection duration: UK Register of HIV seroconverters." (PMID 26225723, 2015). "Only three of the symptomatic patients had CD4+ T-lymphocyte counts above 200cells/μL, and all patients with AIDS had a CD4+ count under 300cells/μL." (PMID 26265965, 2015). "In the multivariate analysis, we found that CD4 cell count, AIDS event, cancer diagnosis occurrence, and the underuse or the absence of cART were associated with overall mortality." (PMID 25884678, 2015). "During HIV chronic infection, sustained activation of CD4+ and CD8+ T cells is associated with depletion of CD4+ T cells and increased risk of disease progression to AIDS." (PMID 26713320, 2015). "The remaining 12 patients with AIDS were asymptomatic, but had CD4+ T-lymphocyte counts below 200cells/μL." (PMID 26265965, 2015). "To date, the RNAi-based agents that have reached clinical testing for HIV/AIDS have relied on ex vivo delivery of lentiviral vectors into specific cell types, such as CD4+ T cells or CD34+ HPCs, which are then transfused back into the patient." (PMID 26019725, 2015). "HIV-1 preferentially infects human CD4+ T-lymphocytes, eventually leading to a depletion of CD4+ cells and the clinical progression to acquired immunodeficiency syndrome (AIDS)." (PMID 26019725, 2015). "CD4 cell count less than 200 cells/μl (signifying the terminal stage of HIV infection (AIDS) was seen in 34.5% patients." (PMID 25857950, 2015). "Infection by P. jirovecii presents as an interstitial pneumonia in immunocompromised hosts, particularly HIV patients; in this group, pneumocystosis is considered an AIDS-definitory condition, when CD4+ T lymphocytes are below 200 cells/μL." (PMID 26106622, 2015).
AIDS (continued). "A total of 177 HIV and/or AIDS patients were identified, 94 (53.1%) were male and 120 (68%) had a CD4 count of less than 200 cells/mL." (PMID 26466398, 2015). "For the AIDS patients that were deceased, only those who initiated cART while at a CD4 count ≥200 cells/mm3 were less likely to die from AIDS-related causes compared to those who didn’t initiate ART at all." (PMID 26506621, 2015). "Antiretroviral therapy (ART) in a majority of patients suppresses HIV plasma viral load (VL) and stops the progression to AIDS, allowing progressive CD4 T cell recovery paired with a persistent elevation of CD8 T cells." (PMID 26130226, 2015). "Mortality decreased from 27%/27% to 10%/10% for all cases (all p < 0.001) and from 40%/35% to 13%/13% for cases with CD4 count ≤ 350 cells/mm3 or AIDS (all p < 0.001)." (PMID 26348214, 2015). "Collectively, a persistently low CD4:CD8 ratio during long-term effective ART represents a marker of continuing immune dysfunction, “inflammaging” and high risk of non-AIDS morbidity and mortality." (PMID 26130226, 2015). "While a significantly higher proportion of those diagnosed late (i.e. with a CD4 count <350 cells/μl or an AIDS defining illness at diagnosis) received HAART (Chi-squared test, P = 0.003)." (PMID 25884351, 2015). "Missed Appointments was predictive of all primary and secondary outcomes, including CD4 cell count ≤500 cells/mm3, progression to AIDS, ED visit, and hospitalization." (PMID 25794182, 2015). "The largest reduction in the rate of AIDS progression was observed in patients with a baseline CD4+ T-cell count of 200–350 cells/mm3 (25.8/100 py of the patients in 2008–2010 and 17.7/100 py of the patients in 2011–2012, P < 0.001)." (PMID 26413133, 2015). "In Europe, over 50% of HIV-positive patients are late presenters (LPs), defined as individuals presenting for HIV care with a CD4 cell count below 350 cells/μl and/or an AIDS-defining event (ADE)." (PMID 26584954, 2015). "In this study, the number of missed appointments significantly predicted a detectable HIV viral load and an AIDS-defining CD4 cell count." (PMID 25794182, 2015). "So we suggest ophthalmoscopic examination and rigorous eye check up must be a compulsory practice in case of every HIV/AIDS patients having CD4 count ≤100 and / if the subject is having serum CMV viremia." (PMID 25679798, 2015). "We recognise that the CD4 count-specific rate of HIV-related symptoms is derived somewhat arbitrarily by doubling the AIDS rate, although it was based on data from more than one study of carefully followed cohorts, including a study of our own." (PMID 25768925, 2015). "Amongst 404 patients who had a complete clinical history, 34% were AIDS presenters and 49.3% had CD4 count ≤350/mm3 at HIV diagnosis." (PMID 26543523, 2015). "Nonetheless, these data are sufficient to allow for comparisons of trends in survival across different periods of diagnosis and CD4 count to AIDS diagnosis during the early years of HAART." (PMID 25886530, 2015). "We assayed five miRNAs in HIV/AIDS patients, which are expressed mainly in B and T lymphocytes, the major constituents of PBMCs, and were previously shown to correlate with CD4+ T-cell counts and viral loads in HIV infected persons." (PMID 24828336, 2014). "Some of these factors include: female sex, increasing age, high HIV viral load, low CD4 cell count, presenting opportunistic infections (clinical AIDS), low body mass index (BMI) and intravenous drug use." (PMID 25005803, 2014). "Multilevel model of the changes in CD4 + T cells count over time for patients living with HIV/AIDS, according to biological and socioeconomic factors, habits, associated diseases, medical care and HIV related factors." (PMID 24505247, 2014).
AIDS (continued). "The initial regimen type selected was found to significantly interact with the relationship of third drug class (p = 0.040), dosing requirements (p = 0.024), previous AIDS events (p = 0.003), and pre-treatment CD4 lymphocyte count (p = 0.049) on efficacy." (PMID 24830290, 2014). "The virus uses CD4 to open the door for invading the T cell, eventually destroying the whole immune system, hence the name of AIDS." (PMID 25087847, 2014). "Chronic immune activation during HIV infection is considered as the main driver of CD4+ T cell depletion and AIDS, and early T cell activation is a better predictor of the outcome of the infection than viral load." (PMID 24991927, 2014). "Patients in group B were older (p<0.001), more likely to be of Italian origin (p<0.001), whereas patients in Group A had lower CD4 cell count at the time of AIDS diagnosis (both p<0.001) than patients with OIs classified in other groups." (PMID 24587081, 2014). "CD4+ immune cells are the main target cells of human immunodeficiency virus (HIV), the etiological agent of acquired immune deficiency syndrome (AIDS)." (PMID 25517345, 2014). "The 15 patients from CT/AIDS group developed focal cerebral toxoplasmosis as they had CD4+ lymphocytes counts less than 100 cells/μl of blood." (PMID 25352834, 2014). "Modern antiretroviral (ARV) drug regimens effectively suppress virus replication, allowing patients to maintain higher levels of CD4 cells and delay the progression to AIDS." (PMID 24866200, 2014). "It is reasonable to assume that with chronically high levels of Nef, the continuous apoptotic stimulus on CD4+ T-cells would lead to low T-lymphocyte counts and finally to T-cell depletion and AIDS." (PMID 24560340, 2014). "Thrombocytopenia is associated with increased morbidity and mortality, accelerated deterioration in CD4 counts and accelerated progression to AIDS." (PMID 24387326, 2014). "Of the patients with missing pre-treatment CD4+ T-cell counts, 46% had a documented AIDS-defining clinical condition 90-days prior to or 30-days post initiating ART compared to 32% of those with a pre-treatment CD4+ T-cell count." (PMID 24919778, 2014). "Clinically, the onset of AIDS is defined as the time point at which the CD4+T-cells count in the blood falls below 200 per microlitre." (PMID 24963975, 2014). "Of these patients, only 41 met the enrolment criteria for this study, i.e. had a detectable CMV VL and a diagnosis of AIDS as defined by CD4 count <200 cells/μl." (PMID 24699683, 2014). "The importance of CD4 counts as a strong predictor of opportunistic infections and non-AIDS events has been widely investigated, but little attention has been paid to the prognostic significance of CD8 counts." (PMID 24831517, 2014). "People with missing data for variables included as continuous (e.g. CD4 count at the date of AIDS diagnosis) were, however, excluded from the multivariable calculations." (PMID 24587081, 2014). "We utilized the SIV model of AIDS to assess the earliest host-virus interactions and mechanisms of inflammation and dysfunction in the gut, prior to CD4+ T cell depletion." (PMID 25166758, 2014). "The cause of the progressive depletion of CD4+T cells in HIV-infected people is one of the most fundamental and controversial issues in AIDS research." (PMID 25136605, 2014). "Monkeys infected with SIVΔvpx had lower viral loads and a slower progression to AIDS than what is typically observed with the parental SIVmac239, but nonetheless progressed to simian AIDS with low CD4 counts and AIDS-defining lesions." (PMID 24465411, 2014). "Among the 31 AIDS-RL (mean age: 43 ± 8 years) of the study, 20 had CD4+ lymphocytes <300/mm3 (mean 133 ± 70/mm3), 11 had CD4+ lymphocytes >300/mm3 (mean 630 ± 260/mm3)." (PMID 25908934, 2014). "Unmatched patients (n=379) had more advanced HIV infection, with lower CD4 cell counts (median 81 vs. 223), higher VL (median 5.2 vs. 4.9) and more frequent prior AIDS-defining event (40% vs. 17%)." (PMID 25261780, 2014).